HIF1A (hypoxia inducible factor 1 subunit alpha)
Diseases named in the same sentence as HIF1A in open-access papers (continued):
Sharing a sentence is not in itself a finding about the gene and the disease.
tumor (continued). "Meanwhile, the upregulation of LDHA mediated by HIF-1α promoted the formation of lactic acid from pyruvate, which contributed to the acidification of the tumor microenvironment." (PMID 35350760, 2022). "With specific respect to the tumor cell-specific interplay between Nrp1 and hypoxia, there is one study to our knowledge that has uncovered a specific interaction between Hif1a and Nrp1." (PMID 36203599, 2022). "Up-regulated HIF-1α expression and increased glycolysis in tumor cells are dependent on the activated PI3K/Akt pathway, regardless of oxygen levels." (PMID 34998404, 2022). "Hypoxic exosomes expressed by various cancer cells significantly upregulate the proliferation of endothelial cells as well as tumor cells, promoting tumor growth via the target of several signaling pathways, including the HIF1α signaling." (PMID 36233088, 2022). "The study found that hypoxia/HIF-1α suppresses antagonistic tumor immune responses and promotes malignant tumor development." (PMID 35280516, 2022). "Based on this phenomenon, a recent study used nanosystems to remotely enhance hyaluronidase activity, promote hyaluronic acid degradation, and reduce HIF-1α expression, alleviating the immunosuppressive tumor microenvironment." (PMID 36387147, 2022). "Upregulation of HIF-1a can promote neovascularization by promoting tumor cells to produce pro-angiogenic factors such as PDGF-B, FGF-2, VEGF-A, VEGFR1 and angiopoietins." (PMID 36319992, 2022). "Viperin is induced in the tumor microenvironment via PI3K/AKT/mTOR/HIF-1α and IFN signaling pathways to promote cancer metabolism." (PMID 36227691, 2022). "In the major part of the tumors an overexpression of HIF-1α protein was found, highlighting how a limited oxygenation in the tumor microenvironment supports the development of the tumor itself and specifically a passage towards metastatic form." (PMID 35870078, 2022). "It was indicated that the HIF-1α expression was significantly decreased in the CIK group's tumor tissue compared to that of the other groups (P < 0.05)." (PMID 35346234, 2022). "Concordantly, inhibition of HIF1α with the camptothecin derivative EZN-2208 exerts anti-tumor activities and acts as a chemosensitizer by interrupting protective microenvironmental interactions of CLL cells both in vitro and in vivo." (PMID 36059690, 2022). "Increased levels of HIF-1α expression promote tumor growth, whereas a reduction in its activity inhibits tumor growth." (PMID 36338690, 2022). "HIF-1α is a key regulator of cellular responses to changes in oxygen concentration, and supports tumor cell adaptation to hypoxia in an oxygen-deprived TME." (PMID 36408139, 2022). "In a model of subcutaneous lung tumor transplantation in rats, intraperitoneal injection of ascorbic acid (1 g/kg) suppressed HIF1α expression in tumors and decreased tumor growth and vascular density." (PMID 36203466, 2022). "Hypoxia in solid tumors induces increased expression of TGF-β1 and HIF-1α, which facilitates tumor growth by inhibiting the antitumor immune response and inducing tumor immune escape." (PMID 36233088, 2022). "In spite of that HIFs-dependent or independent regulated circRNAs exist, the transcription of circRNAs is regulated by HIFs, especially HIF1α, to aid the tumor responses to hypoxia." (PMID 35915091, 2022). "HIF-1α upregulation in tumor MDSCs increased arginine and NO production, which directly upregulated arginine and nitric oxide, with subsequent suppressive effects of MDSCs." (PMID 35769460, 2022). "HIF-1α not only features as a factor that leads to tumor progression but is also a possible mediator in gastric carcinogenesis." (PMID 35681691, 2022). "They further found that HIF-1α expression levels positively correlated with the expression levels of tumor proliferation marker Ki67." (PMID 35993091, 2022). "Although HIF-1α has been described as a tumour suppressor gene in some papers it is a known oncogene." (PMID 35158796, 2022).
tumor (continued). "Salmonella invasion in a tumor can downregulate the expression of HIF-1α and VEGF, and inhibits tumor angiogenesis via the AKT/mTOR pathway." (PMID 36297535, 2022). "Further, common mutations in other tumor suppressors, such as SWI/SNF protein PBRM1, have been linked to the amplification of HIF1α signaling." (PMID 36040300, 2022). "LncSNHG1 can act as an oncogene by regulating Wnt/β-catenin signaling, the PI3K/AKT signaling pathway, and the HIF-1α/VEGF signal pathway in different tumor progression." (PMID 35310912, 2022). "The results obtained suggest that lncRNA SNHG15 regulated tumor growth in murine models via the miR-4735-3p/HIF1a axis." (PMID 35069980, 2022). "These exosomes contain miRNA-301a-3p, which acts as a tumor-promoting factor and increases the stability of HIF-1α and inhibits its degradation by targeting PDH3 and hydroxylating HIF-1α subunits." (PMID 35765040, 2022). "Consistent with the downregulation of these target genes of HIF1α, wBCC showed impaired in vivo tumorigenic ability in the tumor xenograft mouse model and metastatic ability in the lung metastasis mouse model." (PMID 35941273, 2022). "In this review, we discuss the role of HIF-2α in physiology and tumor progression and the differences between HIF-1α and HIF-2α in structure, function, and regulation of the hypoxic response." (PMID 35267567, 2022). "In this study, we found that NBO2 water sensitized radiation reactivity via suppression of radioresistance-related HIF-1α and CA IX expression in a tumor-bearing mouse model, consistent with our previous in vitro data." (PMID 35743281, 2022). "In the cancer milieu, decorin signals through EGFR and Met receptors found on the surface of cancer cells, effectively resulting in decreased HIF-1α and marked angiostasis of the tumour vasculature, suppression of tumour growth and enhanced mitophagy." (PMID 34982945, 2022). "Succinate accumulation was detected in tumors with germline mutation of SDH and cytosolic succinate was recognized as a signal molecule to stabilize HIF-1α and alter tumor behavior." (PMID 36344992, 2022). "Collectively, the data suggest that involvement of HIF2α in the physiology and tumor pathology of human paraganglia is organ-of-origin-dependent and HIF1α-independent." (PMID 35740651, 2022). "Based on this, the hypoxia-inducible factor 1α (HIF-1α) in the tumor section was stained with an immunohistochemical method to carried out for evaluation of tumor hypoxia in vivo." (PMID 35935500, 2022). "TME hypoxic condition contributes to genetic instability, intratumorally heterogeneity, malignant progression, tumor stem cell maintenance, angiogenesis, development of treatment resistance, and metabolic reprogramming dependent on HIF-1α phenotype." (PMID 36176756, 2022). "In the hypoxic tumor microenvironment, the transcription and metabolism of B cells are mainly affected by hypoxia inducible factor-alpha (HIF-1α) and myelocytomatosis virus oncogene cellular homolog (MYC)." (PMID 36212414, 2022). "Hypoxia-inducible factor-1α (HIF-1α), as a transcription factor, plays a key role in cancer progression and can regulate tumor occurrence and development by promoting angiogenesis, cell proliferation, invasion, and metastasis." (PMID 35884611, 2022). "TAMs are involved in angiogenesis and tumor spread through upregulation of hypoxia-inducible factor (HIF)-1a and HIF-2a when they are recruited to the hypoxic environment." (PMID 36131942, 2022). "The tumor hypoxia areas (HIF-1α) in the Endostar and Endostar+PD-L1 groups were significantly lower than those in the control group or the PD-L1 group (P< 0.05)." (PMID 36389685, 2022). "Under hypoxia, tumor angiogenesis increases, tumor cell proliferation and migration accelerate, and Hif-1α is the most important factor." (PMID 35096204, 2022). "Sp1 and HIF-1α overexpression after Bevacizumab treatment is involved in anti-angiogenic resistance in tumor cells." (PMID 35499045, 2022).
tumor (continued). "Hypoxic microenvironment is an important factor inducing tumor metastasis, and HIF1α plays a crucial role in the regulation of hypoxia." (PMID 35589690, 2022). "PD-L1 expression on tumor cells is regulated in part by HIF1α, which binds directly to a hypoxia response element in its proximal promoter." (PMID 35053444, 2022). "It has been found that COMMD1, another member of the COMMD3 family, can inhibit downstream gene expression mediated by the NF-κB pathway via blocking the HIF1α and HIF1β isodimer formation pathway, in turn inhibiting the malignant progression of tumor cells." (PMID 36092163, 2022). "Another mechanism of action of HDACi is the blocking of tumour angiogenesis, through blocking tumour angiogenesis by hyperacetylating and degrading hypoxia-inducible factor (HIF-1a) that acts as a proangiogenic transcription factor." (PMID 35954379, 2022). "The interaction between VHL and HIF1A indicating the involvement of the same pathway to suppress tumor activity." (PMID 35399005, 2022). "Considering the impact of hypoxia and acidosis on tumour perfusion, we know that hypoxia promotes tumour angiogenesis via HIF-1α signalling, while acidosis induces a reversible mechanism of EC-driven angiogenesis inhibition." (PMID 36224457, 2022). "Sustained anti-angiogenesis therapy increases the level of tumor hypoxia, leading to increased expression of HIF-1a, which promotes the production of pro-angiogenesis genes, thereby contributing to the resistance of HCC cells to anti-angiogenesis therapy." (PMID 35140333, 2022). "HIF-1α is activated in the hypoxic tumor microenvironment and modulates many transcription factors that allow cells to survive in unfavorable conditions." (PMID 35769999, 2022). "MUC1 is involved in the vital process of HIF-1α regulating tumor glucose metabolism, leading to increased dependence of tumor cells on glucose and the increase of corresponding pyrimidines, thereby improving the intrinsic level of dCTP." (PMID 35709153, 2022). "For instance, miR-145 acts as a tumor suppressor, and the downregulation of miR-145 in OC contributes to angiogenesis through the upregulation of HIF-1α and VEGF." (PMID 35743145, 2022). "Mast cell-derived HIF-1α in the TME is associated with further expressions of HIF-1α and VEGF in mast cells that enhance tumor growth." (PMID 36233088, 2022). "Notch1 plays an antagonist role with HIF1α and acts as a tumor suppressor in CML patients, which needs further elucidation." (PMID 35847841, 2022). "Immune cells infiltrated at the tumor site also suffer from oxygen starvation resulting in activation of HIF-1α in them." (PMID 36014432, 2022). "A 14q focal deletion is a common abnormality in ccRc; specifically, the deletion encompasses the HIF-1α locus and contributes to a loss of function mutation of the HIF-1α gene, which is otherwise classified as a tumor suppressor." (PMID 35267567, 2022). "Increased expression of O2 at the tumor site down-regulates HIF-1α to affect tumor cell metabolism and negatively regulates Treg cells differentiation." (PMID 36761171, 2022). "The cross talk between TLR4/NF-κB and HIF-1α signaling pathway forms a positive feedback loop and contributes to tumor initiation, malignant progression, and prognosis in EOC." (PMID 35464826, 2022). "In this paper, experiments were conducted on this basis in order to confirm that CA can inhibit the expression of Sept9 and Hif-1α through the Pi3k/Akt pathway, inhibit the tumor microenvironment, and restrict tumor growth." (PMID 35096204, 2022). "The stabilization of HIF‐1α is an important event in tumour progression, allowing tumour cells to adapt to the reduced availability of oxygen by upregulating glycolytic genes and downregulating mitochondrial oxygen consumption." (PMID 35842901, 2022).
tumor (continued). "In the hypoxic microenvironment, tumor cells highly express hypoxia-inducible factor-1 (HIF-1α), which promotes the tumor cell heterogeneity and tumor angiogenesis, as well as tumor cell infiltration and metastasis." (PMID 35615737, 2022). "PKM2 is typically present in tumor cells and can be activated by HIF‐1α in response to oxygen deprivation, cytokines, and oncogenes in the TME." (PMID 35356799, 2022). "Meanwhile, the overexpression of NGF and the increased release of hypoxia-inducible factor-1alpha (HIF-1a) magnify tumor neo-angiogenesis, and this correlated with microvascular density." (PMID 36289793, 2022). "In conclusion, patients with HIF-1α positive primary tumours had a worse outcome with increased recurrences, but these patients still had equal benefit from postoperative RT as patients with a non-hypoxic primary tumour." (PMID 35140341, 2022). "HIF-1α and HIF-2α are associated with the induced expression of genes associated with tumor promotion." (PMID 35625561, 2022). "JMJD2D can also cooperate with SOX9 and c-Fos to induce HIF1α/β expression and serves as a coactivator for HIF1α to promote the transcription of tumor glycolysis-related genes." (PMID 35740507, 2022). "In contrast, HIF1α has a direct role in ameliorating the acute effects of impaired mtDNA expression in IMT1‐treated tumor cells." (PMID 34779571, 2022). "HIF-1α is also involved in the upregulation of the macrophage immune checkpoint CD47 on the surface of tumor cells inducing tumor cell escape from phagocytosis." (PMID 35910347, 2022). "Showed that HIF1a promotes tumor growth and metastasis by promoting anaerobic glycolysis and lactic acid production in a hypoxic environment Semenza (2013)." (PMID 35847977, 2022). "Under normoxia, HIF-1α has also been demonstrated as a major mediator in tumor progression and recurrence." (PMID 34998404, 2022). "Significantly upregulated pathways include glycolysis, pathogen-induced chemokine storm signaling pathway, phagosome formation, tumor microenvironment, Hif1α signaling, and Fcγ receptor-mediated phagocytosis." (PMID 36515985, 2022). "Studies have shown that HIF-1α can promote the malignant progression of tumors through various mechanisms, such as tumor cell invasion, angiogenesis, and immune suppression." (PMID 35847925, 2022). "CA can inhibit expression of vascular endothelial growth factor (VEGF), reduce neovascularization and cancer cell proliferation, and promote cancer cell apoptosis through tumor hypoxia microenvironmental factor Hif-1α." (PMID 35096204, 2022). "The expression level of HIF-1α in secondary malignant tumor tissues is shown to be abnormally increased." (PMID 36277473, 2022). "For example, mTOR inhibitors, known to translationally attenuate HIF-1α protein expression, synergize with rapamycin in reducing tumor growth in preclinical models of hepatocellular carcinoma." (PMID 35499071, 2022). "Our results suggest that the expression of HIF1α is related to tumor prognosis and immune cell infiltration." (PMID 35860430, 2022). "Hypoxia leads to decrease in HIF-1α degradation resulting in pro-angiogenic potential as well as potentiation of tumor induced immunosuppression." (PMID 35012617, 2022). "The hypoxia-inducing factor HIF1α has been revealed in previous studies to play a key role in tumor recurrence and metastasis." (PMID 36473847, 2022). "Tanespimycin was found to inhibit Hsp90-implicated HIF-1α signaling, including HIF-1α destabilization and VEGF secretion, consequently suppressing angiogenesis and tumor growth." (PMID 36551540, 2022). "Hypoxia also markedly increases PD-L1 expression in dendritic cells, macrophages, and tumor cells in an HIF1A expression-dependent manner." (PMID 35659268, 2022). "As a proverbial hypoxic response factor, HIF-1α elicits the indispensable role in tumor hypoxic microenvironment and is involved in multiple aspects of tumor progression, including cancer growth, angiogenesis, and chemoresistance." (PMID 34969360, 2022).
tumor (continued). "In contrast, in the peripheral regions, the level of HIF-1α protein was clearly lower in Dox− tumor lysates than in the core." (PMID 36183290, 2022). "Thereby, HDAC1 stimulates oxygenation of the tumor microenvironment by upregulating HIF-1α expression through HDAC1/MTA1." (PMID 35327319, 2022). "The key to the adaptation of tumor cells to hypoxia is the transcriptional and stable expression of hypoxia-inducible factor-1 alpha (HIF-1α)." (PMID 35413842, 2022). "Transcription of gene-encoding glycolytic enzymes is activated by HIF-1α, including stimulation of glycolysis by upregulation of LDHA, which creates an acidic tumor microenvironment." (PMID 35342404, 2022). "Treatment with LENP-Gem-si-HIF1α results in effective silencing of HIF1α both in vitro and in vivo as well as significant synergistic tumor growth inhibition." (PMID 35057033, 2022). "It has been reported that the expression level of HIF-1α in tumor specimens is positively correlated with the aggressiveness and poor prognosis for cancer patients with conventional therapy." (PMID 35684364, 2022). "Although HIF1α and HIF2α share many of the same target genes, HIF1α is postulated to act as a tumor suppressor while HIF2α has a pro-oncogenic function in ccRCC." (PMID 36284084, 2022). "Cluster 2 was similar to cluster 1 in gene expression; however, the high expression of mmp2 and Hif1a indicated that it was tumor neovascularization endothelial cell (tumor neo vEC)." (PMID 36382024, 2022). "Namely, the structure, function, and role of HIF-1α in tumor progression have been thoroughly reviewed." (PMID 35267567, 2022). "In order to examine the CAT function of relieve tumor hypoxia, tumors were collected 6 h after the last irradiation for examining the expression level of HIF‐1α by western blotting." (PMID 35715382, 2022). "Studies have confirmed that hypoxic tumor cells overexpress HIF-1α and P-gp, which observably promote the progress of cancer cells resistant to small-molecule targeted drugs." (PMID 36015232, 2022). "CAFs in TME can produce tumor-associated cytokines, such as IL-6, NF-κB, and TGF-β2, which support their function by enhancing secretion of HIF-1α and forming a feedback loop facilitating tumor migration and invasion by shaping the immunosuppressive TME." (PMID 35794625, 2022). "Hypoxia-induced upregulation of HIF-1a can mediate tumor cell de-differentiation into CSCs, which is a primary mechanism that underlies resistance to anti-angiogenesis therapy." (PMID 35281003, 2022). "Hypoxia-inducible factor 1 alpha (HIF1α) promotes tumor cells to obtain stronger proliferation, invasion and metastasis capabilities under the metabolic stress conditions." (PMID 35589690, 2022). "It is becoming more and more apparent that the elevated anti-tumor immunity by high-dose irradiation is often counterbalanced or negated by the overwhelming immunosuppressive TME enriched with HIF-1α." (PMID 35805044, 2022). "Immunohistochemistry of tumor tissues revealed a strong co-expression between HIF-1α, Foxp3 and TGF-β." (PMID 35625561, 2022). "Hypoxia contributes to the evasion of innate immunity by increasing the expression of the metalloproteinase ADAM10 in tumor cells in dependence on the accumulation of HIF-1α." (PMID 35574385, 2022). "The immunohistochemistry of tumor tissues revealed decreased Ki-67, HIF-1α, and VEGF expression in the chrysin-treated group compared to an untreated control." (PMID 36139362, 2022). "One of the most important factors of hypoxia is the hypoxia-inducible factor (HIF-1α), a transcription factor crucial for oxygen homeostasis and energy metabolism, cell survival, and tumor invasion." (PMID 36555323, 2022). "BRD4 inhibition was also shown to decrease M2 tumor-associated macrophage (TAM) proliferation, particularly by directly inhibiting HIF1α expression in tumor cells, thereby inhibiting the secretion of M2-promoting colony-stimulating factor 1 (CSF1)." (PMID 36139513, 2022).